S100B (S100 calcium binding protein B)
Diseases named in the same sentence as S100B in open-access papers (continued):
Sharing a sentence is not in itself a finding about the gene and the disease.
Alzheimer disease (continued). "Micromolar amounts of S100B protein produce neuronal death, as seen in several neuropathologies, such as Alzheimer's disease and Down syndrome." (PMID 24790767, 2014). "Elevated antibody titers for S100B and other brain protein have been described in a variety of human diseases including Alzheimer's dementia." (PMID 23483891, 2013). "Increased S100B levels are observed in patients suffering from chronic neurodegenerative disorders such Alzheimer’s disease." (PMID 24359080, 2013). "Some previous studies have showed that the levels of serum S100B were significant higher in patients with obstructive sleep apnea syndrome (OSAS) or Alzheimer’s disease." (PMID 24359080, 2013). "S100B proteins are low-molecular weight proteins which often increase in chronic epilepsy, Alzheimer's disease, and head trauma." (PMID 21837247, 2012). "In Alzheimer's disease the pattern of S100B overexpression correlates with the pattern of neuritic-plaque formation." (PMID 21445240, 2011). "Increasing evidence suggests that the small EF-hand calcium-binding protein S100B plays an important role in Alzheimer's disease." (PMID 20672051, 2010). "In this paper we discuss the current literature regarding the role of S100B/RAGE activation in Alzheimer's disease." (PMID 20672051, 2010). "Based on genetic and pharmacological lines of evidence, we consider such deleterious roles of S100B in two common brain pathologies: ischemic stroke and Alzheimer's disease (AD)." (PMID 20862385, 2010). "Numerous studies have reported that increased expression of S100B, an intracellular Ca2+ receptor protein and secreted neuropeptide, exacerbates Alzheimer's disease (AD) pathology." (PMID 21080947, 2010). "Elevated brain S100B expression occurs in various disease states, including Alzheimer's disease (AD) and Down syndrome (DS)." (PMID 20827311, 2010). "High levels of S100B in cerebrospinal fluid (CSF) and peripheral blood have been observed in clinical research on Alzheimer's disease, stroke, traumatic brain injury, meningoencephalitis, mood disorders and schizophrenia." (PMID 17199889, 2007). "An increase in brain levels of S100B has been reported in Alzheimer’s disease." (PMID 40722873, 2025). "Similarly, alterations in S100B expression have been reported in Alzheimer’s disease and depression, where gut microbiota dysbiosis has also been recognized as a contributing factor." (PMID 40723919, 2025). "On the one hand, elevated circulating levels of S100B have been associated with risk of Schizophrenia (SCZ), bipolar disorders (BIP), major depression disorder (MDD), autism spectral disorders (ASD), and Alzheimer’s disease (AD)." (PMID 37225692, 2023). "S100B has been discovered in a wide variety of neurodegenerative diseases and appears to play a role in the progression of the pathophysiological processes of Alzheimer's disease during the early stages of this disease." (PMID 36618764, 2022). "Chromosomal rearrangement and expression changes of S100B gene have been verified to be related to several nervous system diseases, neoplastic diseases, endocrine diseases like Alzheimer’s disease (AD), Down’s syndrome, epilepsy, amyotrophic lateralizing sclerosis, tumor and type 1 diabetes." (PMID 36213260, 2022). "To provide insight into the molecular regulation of S100β and its potential causal associations with Alzheimer’s disease, we carried out genome- and epigenome-wide association studies (GWAS/EWAS) of serum S100β levels in older adults and performed Mendelian randomisation with Alzheimer’s disease." (PMID 35028426, 2021). "Colocalisation between S100β and Alzheimer’s disease GWAS loci was also examined." (PMID 35028426, 2021). "Increased CSF or serum S100B levels were found in different acute and chronic brain disorders, such as traumatic brain injury, ischemic stroke or Alzheimer’s disease." (PMID 32792937, 2020).
Alzheimer disease (continued). "Furthermore, S100B—mainly concentrated in astrocytes—is recognized as a reliable biomarker of active neuronal distress in Alzheimer’s disease, Parkinson’s disease, ALS, or multiple sclerosis." (PMID 31671515, 2019). "S100β produced by astrocytes is a common feature of Alzheimer disease." (PMID 31611796, 2019). "However, S100B was also shown to activate p38, ERK1/2 and JNK in Alzheimer's disease, of which S100B mediated JNK and ERK1/2 activation seems again be dependent on the presence of RAGE." (PMID 22227007, 2012). "Among them S100B, S100A6, S100A9 and S100A12 have been linked to Alzheimer's Disease." (PMID 20672051, 2010). "Moreover, S100B TG mice show increased susceptibility to perinatal hypoxia-ischemia, and overexpression of S100B has been shown to accelerate Alzheimer disease-like pathology with enhanced astrogliosis and microgliosis." (PMID 20827421, 2010). "Both of these processes are therefore accelerated towards degeneration in disease processes wherein S100B is increased, notably, Alzheimer's disease (AD) and Down syndrome (DS).In order to study the role of S100B in this context, we have examined S100B overexpressing transgenic mice." (PMID 20827311, 2010). "Engagement of RAGE by S100B could thus contribute to the chronicity of inflammation observed to Alzheimer's disease." (PMID 20672051, 2010). "This may have arisen from several postmortem studies on Alzheimer's disease and Down's syndrome describing predominant S100B immunostaining in reactive astrocytes surrounding neuritic plaques." (PMID 17199889, 2007). "S100B is predominantly secreted by astrocytes in the nervous system and may be involved in the pathological mechanisms of neurodegenerative diseases, such as Alzheimer’s disease (AD) and Parkinson’s disease (PD)." (PMID 40920789, 2025). "Although the exact pathophysiology is still unknown, a number of small-scale studies have reported elevated circulating or cerebrospinal fluid (CSF) S100β levels in individuals with nervous system injury, neuroinflammatory conditions, white matter ageing and Alzheimer’s dementia and delirium." (PMID 35028426, 2021). "This may be evidenced by our lack of causal association to Alzheimer’s disease and these pathways should be explored to delineate targets for therapeutic interventions that may alter neuroinflammation through S100β mediation." (PMID 35028426, 2021). "Whether S100β has a direct involvement in the pathogenesis of Alzheimer’s disease is still unclear." (PMID 35028426, 2021). "The lack of evidence for a causal relationship between S100β and Alzheimer’s disease suggests either that 1) S100β levels in the blood are not directly related to the disease, or 2) any associations are more modest than this study is powered to reliably detect." (PMID 35028426, 2021). "Thus, it is tempting to speculate that the role of S100B in Alzheimer's disease is mediated by RAGE and numerous studies mentioned in this paper support this hypothesis." (PMID 20672051, 2010). "Elevated levels of serum S100B, a potential biomarker of BBB disruption, have been observed during delirium in Alzheimer’s disease and critical illness." (PMID 27810376, 2017). "Studies have shown that enhanced S-100β upregulated the cyclooxygenase-2 expression by way of RAGE in microglia, and in those with Alzheimer disease cyclooxygenase-2 inhibitor impeded neuro-inflammation and induced amelioration of cognitive function." (PMID 24236147, 2013). "Alzheimer's disease is a complex disease involving many molecular partners including RAGE and S100B." (PMID 20672051, 2010). "We evaluated serum levels of S100B and neuron-specific enolase (NSE) in 54 mild, moderate and severe Alzheimer's disease (AD) patients and in 66 community-dwelling elderly." (PMID 20105309, 2010).
Alzheimer disease (continued). "The Alzheimer’s disease biomarkers did not reveal a time dependency of the interval between sampling, whereas the ventricular-lumbar differences of S100B and NfL became slightly more prominent with sampling interval." (PMID 36670437, 2023). "Besides S100B, RAGE can also be engaged by other ligands that are all relevant in Alzheimer's disease." (PMID 20672051, 2010). "S100-β protein serves as a biomarker for evaluating the severity of brain injury in various neurological conditions, including traumatic brain injury without multiple trauma, acute stroke and Alzheimer’s disease and others." (PMID 40642216, 2025). "While the role of S100b proteins in Alzheimer's disease pathophysiology is not well understood, a recent meta‐analysis demonstrated significantly higher levels of CSF neurone specific enolase in patients with Alzheimer's disease." (PMID 39668510, 2025). "Colocalisation analyses provided further evidence that the loci for Alzheimer’s disease and S100β were not localised together (Hypothesis 2: Posterior Probability (PP) = 0.99, Hypothesis 3: PP = 0.01, Hypotheses 1 and 4 = 0)." (PMID 35028426, 2021). "S100B and APP can be seemed to be multiple pathogenesis and co-occurrence of MS with DS and Alzheimer’s dementia may advance more severely than MS without DS." (PMID 40395918, 2025). "Although there is evidence for metabolic dysfunction and chronic inflammation in Alzheimer's disease (AD), circulating levels of soluble receptor for advanced glycation end products (sRAGE) and the receptor for advanced glycation end products (RAGE) ligand S100B have not been characterized." (PMID 29681765, 2018).
brain injury (84 papers, 2008 to 2025). Acute and chronic (see also brain INJURIES, CHRONIC) injuries to the brain, including the cerebral hemispheres, CEREBELLUM, and brain STEM. "Recently, a French retrospective study was conducted to evaluate the impact of implementing a modified PECARN rule including the S100B protein assay for managing mTBI in children at intermediate risk for clinically important traumatic brain injury." (PMID 37047574, 2023). "S100B has been suggested to be effective in identifying concussion and more severe forms of TBI; however, subtle changes caused by subconcussive head impacts are more challenging to detect." (PMID 33096545, 2020). "Intraventricular infusion of low concentrations of S100B induces neurogenesis within the hippocampus in a traumatic brain injury model, and this was associated with enhanced cognitive function." (PMID 24137128, 2013). "S100B, a calcium-binding protein primarily found in glial cells, has been implicated in various physiological and pathological processes in the central nervous system Elevated S100B levels are associated with issues like brain injuries, strokes, infections, and neurodegenerative disorders." (PMID 37762178, 2023). "One may speculate that the higher S100B levels observed are merely a reflection of the increased risk of brain injury these patients have following brain trauma." (PMID 23830006, 2013). "In addition to its role as a predictive biomarker, S100B may also act as an active factor participating in pathogenic molecular processes accompanying acute brain injury." (PMID 37047574, 2023). "UCHL1, which has a more specific tissue distribution than S100B, is found more exclusively in neurons and is associated with traumatic brain injury, but it was unclear whether it could play a role in BBB disorders caused by microbial factors (e.g., gp120) and drugs of abuse." (PMID 23637989, 2013). "S100B is released into the bloodstream and cerebrospinal fluid (CSF) following CNS injuries such as traumatic brain injuries, cerebral hemorrhage, and ASCI." (PMID 40125181, 2025). "Potential biomarkers like NSE and S100B have been evaluated for the detection of early-stage perioperative brain injuries following cardiac surgery." (PMID 40310303, 2025). "While some researchers were able to establish a connection between elevated NSE and S100B levels and brain injuries in patients who underwent CEA, others failed to confirm this correlation." (PMID 40310303, 2025). "It has been shown that the S100B level is significantly increased in psychiatric diseases, traumatic brain injuries, cerebrovascular pathologies, and neurodegenerative diseases." (PMID 38918365, 2024). "Previous studies have shown that tau protein and S100B have significant value in estimating brain damage, for instance, brain trauma, ischemic stroke, and cerebral hemorrhage." (PMID 38481189, 2024). "Specifically, only S100B remained stable during the season, indicating its reliability as a biomarker of inconclusive sport-related concussion." (PMID 38397046, 2024). "s-100β is a Ca2+ binding protein secreted by astrocytes, and high levels of extracellular s-100β have been detected in brain trauma, ischemia, neurodegenerative, and inflammatory and psychiatric diseases." (PMID 40224600, 2023). "Preterms with brain injury proved to have significant increase of S100B and NSE, followed by increase of EPO and enhanced mobilization mainly of HSCs, eEPCs and lEPCs." (PMID 37292373, 2023). "On the other hand, the S100B-induced promotion of hippocampal progenitor cell proliferation following experimental brain injury has received less attention." (PMID 36076994, 2022). "An animal experimental study found that S100B enhanced nerve regeneration and plasticity by promoting hippocampal synaptogenesis and synaptic formation after traumatic brain injury." (PMID 35615727, 2022). "S100B is highly expressed in the astroglial cells, with elevated levels in serum following traumatic brain injuries." (PMID 31907552, 2021).
brain injury (continued). "The overall AUC for detecting CT−/MRI+ vs. CT−/MRI− brain injury was 0.839 (95% CI 0.748–0.929, p < 0.001), with a sensitivity of 84.8% and specificity of 74.3% at a S100B cutoff of 0.105 ug/L." (PMID 32098419, 2020). "The S100B protein is to this day the only brain trauma biomarker used in routine in Europe and this study was conducted to explain the limited performances of S100B in emergency departments where ski-related accidents represent a significant percentage." (PMID 32922357, 2020). "Using kinetic modeling, researchers demonstrated that S100B concentration changes dramatically over timescales, and that the peak for its level was found to be at 27.2 h after traumatic brain injury." (PMID 32085663, 2020). "The primary aim of this study was to investigate the correlation and agreement of capillary and venous serum S100B protein level over a spectrum of concentrations typical for mild traumatic brain injury." (PMID 31477027, 2019). "Astrocyte-enriched marker, S100B, shows promise for gauging the severity of acute brain trauma, and understanding subconcussive effects will advance its utility in tracking real-time acute brain damage." (PMID 31024425, 2019). "The performances of H-FABP and S100B biomarkers at 100% sensitivity, ≤ 6 h post-trauma in mTBI subgroups; isolated brain trauma or multiple trauma patients." (PMID 28419114, 2017). "Biomarkers of brain injuries such as S-100B and NSE were considered reliable prognostication tools but therapeutic hypothermia shifted the previously validated thresholds." (PMID 28282398, 2017). "The most studied protein “biomarker” of cerebral damage in traumatic brain injury (TBI) is the protein S100B." (PMID 27957604, 2017). "After brain injuries, concentrations of some brain markers such as S100B protein in serum and cerebrospinal fluid (CSF) are correlated with the severity and outcome of brain damage." (PMID 28761630, 2017). "High concentrations of extracellular S100-B, which result in apoptosis, can be observed in conditions such as brain trauma and inflammatory diseases." (PMID 28352122, 2017). "For mTBI patients with isolated brain trauma the S100B slightly increased to 9% specificity when sensitivity was set to 100%." (PMID 28419114, 2017). "Elevated serum levels of S100B correlate with MRI abnormality and neuropsychological examination after mild traumatic brain injury." (PMID 27468268, 2016). "S100b is an astrocyte related marker of brain injury used primarily in traumatic brain injury (TBI)." (PMID 27315805, 2016). "Serum concentrations of NSE and S100B were significantly correlated with contusion volume, but the 1st sample taken was the most valid indicator of traumatic brain injury severity." (PMID 27468268, 2016). "Data of serial serum S100b samples from 154 traumatic brain injury patients in a neurointensive care unit were retrospectively analysed, including only patients without secondary peaks of this biomarker." (PMID 27315805, 2016). "Enthusiasm for the use of S100B to aid in the diagnosis of concussion, however, has been tempered by significant overlap between levels in healthy individuals and in athletes who have had a concussion." (PMID 24416325, 2014). "By using an intra-subject, before-and-after study design, we minimized the effect that individual-level variation in baseline S100B levels has on obscuring group-level post-concussion increases." (PMID 24416325, 2014). "In an effort to unlock the diagnostic potential of S100B, we sought to compare subject-specific changes in S100B before and after concussion among collegiate and semi-professional athletes." (PMID 24416325, 2014). "Explanations for this observation range from exertion-related release of small amounts of S100B from melanocytes, chondrocytes and adipocytes, to occult or unreported brain injury, or a combination of the two." (PMID 24416325, 2014).